IFIH1 (interferon induced with helicase C domain 1)
Diseases named in the same sentence as IFIH1 in open-access papers (continued):
Sharing a sentence is not in itself a finding about the gene and the disease.
asthma (14 papers, 2011 to 2026). "We also identified a novel association of the IFIH1 loss-of-function allele rs1990760-C (p.T946A) with risk of asthma." (PMID 30327483, 2018). "DDX58 (RIG-I) and IFIH1 (MDA5) mRNA was expressed in HBECs from both controls and patients with asthma at baseline." (PMID 37087523, 2023). "pLOF variants in the gene GPR151 protect against obesity and type 2 diabetes, in the gene IL33 against asthma and allergic disease, and in the gene IFIH1 against hypothyroidism." (PMID 29691411, 2018). "We also identified independent missense associations for genes and phenotypes such as ENPEP and hypertension; GSDMB and asthma; IFIH1 and hypothyroidism; and PALB2 and lung cancer." (PMID 29691392, 2018).
vitiligo (14 papers, 2018 to 2025). Generalized well circumscribed patches of leukoderma that are generally distributed over symmetric body locations and is due to autoimmune destruction of melanocytes. "In conclusion, although the mechanisms by which IFIH1 polymorphisms contribute to vitiligo pathogenesis remain to be explored, it is clear that the IFIH1 gene locus has a role in GV susceptibility." (PMID 30761886, 2019). "Genome-wide association studies of vitiligo detected that the association of IFIH1 functional variants (missense SNPs rs2111485, rs1990760, rs3747517, rs35667974) was protective." (PMID 30761886, 2019). "All missense variants of IFIH1, i.e. rs1990760 (A946T), rs3747517 (H843R), and rs35667974 (l923V), showed association with vitiligo in the independent replication study and the former two showed associations in all three GWASs." (PMID 30761886, 2019). "Several common variants in IFIH1, the most associated variant being the rs2111485, showed highly significant association with vitiligo." (PMID 30761886, 2019). "No population-based, randomized controlled study has been reported since then to confirm the association between IFIH1 and vitiligo." (PMID 30761886, 2019). "Recent genome-wide association studies have led to the identification of function-reducing mutations in interferon induced with helicase C domain 1 (Ifih1) as protective against vitiligo in humans." (PMID 29723194, 2018). "MDA5 is encoded by IFIH1 which is recognized as one of the vitiligo susceptibility genes." (PMID 35884944, 2022). "Additionally, genes related to innate immunity including NALP1, TICAM1, IFIH1 are recognized as vitiligo susceptibility genes." (PMID 35884944, 2022). "IFIH1 is one of the most significantly associated loci with vitiligo." (PMID 30761886, 2019). "Moreover, it has been previously observed that the intracellular innate immune receptor IFIH1 induces type I IFNs and that IFIH1 is implicated in autoimmune processes, and is one of the susceptibility loci/risk genes for vitiligo." (PMID 30515176, 2018). "IFIH1, encoding MDA5 which is an intracellular virus sensor, has been identified as a vitiligo susceptibility gene." (PMID 32532953, 2020). "Furthermore, IFIH1, encoding intracellular virus sensor MDA5, has been identified as a vitiligo susceptibility gene capable of inducing secretion of CXCL10 and CXCL16 from keratinocytes and inducing infiltration of CD8+ T cells in vitiligo." (PMID 33936032, 2021). "In addition to CXCL10, IFN-induced IFIH1 was upregulated in vitiligo skin in the current study." (PMID 30515176, 2018).
enterovirus infection (12 papers, 2010 to 2024). "Presumably, variants associated with reduced IFIH1 function would confer the host with a mild antiviral response to enterovirus infection." (PMID 22110759, 2011). "The protective alleles are functionally deleterious to IFIH1, effectively reducing the ability to mediate an immune response against enterovirus infection." (PMID 20808933, 2010). "It has also been recently shown that the variants in the antiviral response gene IFIH1 associated with protection against enterovirus infection simultaneously increase susceptibility to Type 1 Diabetes (T1D)." (PMID 20808933, 2010). "In this case, the benefits of having variants of the IFIH1 gene that increase susceptibility to T1D depend on the prevalence of enterovirus infection." (PMID 20808933, 2010). "Furthermore, the minor alleles of IFIH1 associated with T1D have reduced activity against enterovirus infections." (PMID 28212332, 2017). "Conceivably, the IFIH1 polymorphisms might influence not only the intensity of inflammation following enterovirus infection, but also the frequency and timing of enterovirus infection, and thus modify the likelihood of prediabetic autoimmunity." (PMID 23144876, 2012). "We cannot exclude weak to moderate effects of the rare variants because of limited power, but the possible existence of such weak effects of rare IFIH1 variants on enterovirus infections would have limited population impact on the epidemiology of enterovirus infections, if any at all." (PMID 22110759, 2011). "IFIH1 is expressed in human islets and β-cells and is crucial for the immune response to enterovirus infection or exposure to synthetic dsRNA (polyinosinic:polycytidylic acid, poly(I:C))." (PMID 28212332, 2017). "Consequently, many studies have investigated the functional aspect of IFIH1 in T1D and also in enterovirus infections." (PMID 31401790, 2019). "One reason for lack of association could be the involvement of complementary innate antiviral pathways, such as those involving the Toll-like receptors, explaining why IFIH1 was not essential for IFN-production after an enterovirus infection in mda5 knockout mice." (PMID 22110759, 2011).
multiple sclerosis (11 papers, 2019 to 2025). A progressive autoimmune disorder affecting the central nervous system resulting in demyelination. "The IFIH1 variant rs1990760 is associated with risk of T1D, SLE, RA, and multiple sclerosis (MS) and results in an amino acid change from alanine to threonine at position 946 in the C-terminal of the interferon-induced helicase C-domain containing protein 1 (IFIH1 also known as MDA5)." (PMID 35979360, 2022).
breast carcinoma (10 papers, 2013 to 2025). "However, the mRNAs of TLR3, Ifih1/MDA5, Zbp1, Ddx60 and Ifi204 were upregulated by varying degrees after poly(I:C) transfection in both mammary carcinoma and fibrosarcoma cells." (PMID 35737804, 2022). "Interestingly, the gene sets of ISs (AIM2, IFIH1 and TLR3), ISs and IFN-β (IFNB1), and all (ISs, IFNB1, IRF7 and TRAIL) showed strong correlations in ER-negative and lymph node positive or basal-like breast cancer patient survival." (PMID 27077807, 2016).
Singleton-Merten syndrome (10 papers, 2019 to 2024). "Pathogenic variants in IFIH1 have previously been associated with the classic Singleton-Merten syndrome, while variants in DDX58 has been described in association with a milder phenotype, which is suggested to have a better prognosis." (PMID 30574673, 2019). "In 2015, a p.Arg822Gln substitution in IFIH1 was shown to cause Singleton Merten syndrome (SMS), an autosomal dominant trait variably characterized by a deforming arthropathy, abnormal tooth development and cardiac valve calcification, again in association with enhanced type I interferon signaling." (PMID 31898846, 2020).
HIV-1 infection (9 papers, 2016 to 2025). The type species of lentivirus and the etiologic agent of acquired immunodeficiency syndrome (AIDS). "Conversely, inhibition of IFIH1 (MDA5) expression did not have any effect on HIV-1 infection." (PMID 29042669, 2017).
ovarian carcinoma (9 papers, 2015 to 2026). A malignant neoplasm originating from the surface ovarian epithelium. "On the other hand, the overexpression of IFIH1 is involved in ovarian cancer drug resistance, indicating the role of IFIH1 is cancer‐dependent." (PMID 35810383, 2022). "IFIH1 is overexpressed in several topotecan-resistant ovarian cancer cell lines; thus, the gene might participate in the drug resistance mechanism of the tumor." (PMID 33777092, 2021).
acute respiratory distress syndrome (8 papers, 2021 to 2025). Progressive and life-threatening pulmonary distress in the absence of an underlying pulmonary condition, usually following major trauma or surgery. "In a study on the molecular regulation of M1 macrophages in acute respiratory distress syndrome, IFIH1 was identified as a novel regulator of M1 macrophage polarisation and a potential therapeutic target." (PMID 36567857, 2022). "IFIH1 contributes to the polarization of M1 macrophages in acute respiratory distress syndrome." (PMID 34868310, 2021).
Encephalopathy (8 papers, 2020 to 2026). Encephalopathy is a term that means brain disease, damage, or malfunction. "If biallelically mutated, IFIH1 and SAMHD1 are among the genes causing the autosomal recessive Aicardi-Goutières syndrome (AGS), a type I interferonopathy leading to an early-onset progressive encephalopathy with basal ganglia calcifications." (PMID 41546701, 2026).
malaria (8 papers, 2016 to 2023). Malaria is a serious and sometimes fatal disease caused by a parasite that commonly infects a certain type of mosquito which feeds on humans. "These transcripts belong to three genes: IFIH1, TGFB2 and PRKCA, and are associated with three KEGG pathways all related to infection and infection detection (RIG-I-like receptor signaling pathway, Malaria, and African trypanosomiasis)." (PMID 38161589, 2023).
Opportunistic infection (8 papers, 2017 to 2025). An infection that is caused by a pathogen that would generally not be able to cause an infection in a host with a normal immune system. "This case shows that AGS with GOF mutation in the IFIH1 gene could mimic CID with opportunistic infections associated with autoimmune and hyperinflammatory manifestations." (PMID 36685504, 2022). "Based on the disease course in our case, it appears that patients with AGS with the IFIH1 GOF mutation may present similarly to patients with CID, with opportunistic infections associated with autoimmune and hyperinflammatory manifestations." (PMID 36685504, 2022). "This spectrum of IFIH1 GOF mutations with overlapping features of hyperinflammation and severe opportunistic infection, which mimics combined immunodeficiency (CID), has not been described before." (PMID 36685504, 2022).
hypothyroidism (7 papers, 2018 to 2025). Abnormally low levels of thyroid hormone. "Clinically manifest extraneurological illness was uncommon in our series, but there appears to be a real association between IFIH1 gain-of-function and lupus-like illness, autoimmune hepatitis, and hypothyroidism." (PMID 31898846, 2020). "In addition, IFIH1 has also been proved to be significantly associated with the risk of hypothyroidism in the UK Biobank." (PMID 34671386, 2021). "We identified additional protective associations between PTVs in IFIH1 and hypothyroidism (labeled as hypothyroidism/myxedema) (MAF = 1.5%, p = 1.7 × 10−6, OR = 0.80, 95% CI: 0.73–0.88) and VKORC1 and hypertension (MAF = 25.3%, p = 1.4 × 10−6, OR = 0.97, 95% CI: 0.96–0.98)." (PMID 29691392, 2018). "A common genetic etiology was proposed between hypothyroidism and OLP81 and our study supports this, indicating variation at nine loci (IFIH1, LPP, CEP43, TNRC18, C12orf42, TNFSF11, ST3GAL6, IL2RA, and IKZF3) that are strongly associated with both LP and autoimmune hypothyroidism." (PMID 38776927, 2024).
glaucoma (6 papers, 2019 to 2024). Increased pressure in the eyeball due to obstruction of the outflow of aqueous humor. "Of note, IFIH1 was the only interferon-related gene identified in DEG analysis which has been associated with glaucoma in literature." (PMID 38272457, 2024). "IFIH1-related SGMRT also features glaucoma in a smaller fraction of cases (~40%) and up to 13.5% of pathogenic variant carriers can be asymptomatic." (PMID 34573386, 2021). "In the case of MDA5, a missense mutation in the IFIH1 gene (c.2465G>A; p.Arg822Gln) has been identified as the cause of classical SMS, characterized by dental anomalies, aortic and valvular calcification, glaucoma, and an enhanced type I IFN signature gene expression pattern." (PMID 39143032, 2024). "In a large study on AGS, glaucoma was reported in 6.3% (23 patients), including 20.8% (10/48 patients) with SAMHD1 pathogenic variants and no patients with pathogenic variants in ADAR or IFIH1." (PMID 34573386, 2021).
glioma (6 papers, 2020 to 2026). A benign or malignant brain and spinal cord tumor that arises from glial cells (astrocytes, oligodendrocytes, ependymal cells). "Potential glioma risk genes with a pathogenic GV most frequently played roles in cell adhesion (CTNND1, EPCAM), immune response (IFIH1, SAMHD1), and ion transport (SLC4A7, TRPM1)." (PMID 41546701, 2026). "Other gene functions implicated in glioma risk in this study include signal transduction (e.g. EGFR), cell adhesion (e.g. GJB2), immune response (e.g. IFIH1 and SAMHD1), and ion transport (e.g. CFTR)." (PMID 41546701, 2026).
Graves disease (6 papers, 2009 to 2019). Graves' disease is an autoimmune disorder that leads to overactivity of the thyroid gland (hyperthyroidism).It is caused by an abnormal immune system response that causes the thyroid gland to produce too much thyroid hormones. "IFIH1 has been associated with Type 1 diabetes (T1D), IgA deficiency, Graves' disease, and suggestively linked to SLE." (PMID 23441136, 2013). "In conclusion, our data suggest, no contribution from IFIH1 rs1990760 polymorphism to the pathogenesis of either Graves' disease, Hashimoto's thyroiditis or Addison's disease in our study populations." (PMID 19961590, 2009).
psoriatic arthritis (6 papers, 2017 to 2025). Joint inflammation associated with psoriasis. "Patients with nail involvement had higher CXCL10 expression; longer duration of the disease was associated with further decrease of CCL27 in areas that were not affected with psoriatic rash; and psoriatic arthritis was associated with lower IFIH1 expression." (PMID 28790368, 2017).
atherosclerosis (5 papers, 2016 to 2025). A disease characterized by the build-up of fatty material and calcium deposition in the arterial wall resulting in partial or complete occlusion of the arterial lumen. "IFIH1, IFIT1, IFIT2, IFIT3, ISG15 and OAS3 had similar expression differences to the training set and had good diagnostic abilities for atherosclerosis." (PMID 36437453, 2022). "IFIH1 was found to be an immune-related hub gene of atherosclerosis and may be a potential target for patients with atherosclerosis." (PMID 40950552, 2025). "Our study identified IFIH1, IFIT1, IFIT2, IFIT3, ISG15 and OAS3 as immune-related hub genes of atherosclerosis." (PMID 36437453, 2022).
Sepsis (5 papers, 2022 to 2024). Sepsis is defined as life-threatening organ dysfunction caused by a dysregulated host response to infection. "The specific expression of IFI44 and IFIH1 in B cells with high PANscores underscores their pivotal role in modulating immune responses in sepsis." (PMID 38239341, 2023). "IFI44 and IFIH1 were specifically expressed in cell populations with a high PANScore, potentially linking these genes to active immune responses in B cells and implicating them in the pathophysiology of sepsis." (PMID 38239341, 2023). "We observed an upregulation in the expression of IFI44, IFIH1, IFIT1, IFIT2, and RSAD2 in lung tissues from animals suffering from sepsis." (PMID 38239341, 2023). "Besides TLR4, several genes, including IFIH1 and STAT1, can affect M1 macrophage polarization and contribute to the progression of sepsis." (PMID 39294473, 2024). "Additionally, ZBP1, XAF1, IFI44L, SOCS1, and PARP14 were notably high in HighPANscore cells, aligning with our observations of upregulated expression of IFI44, IFIH1, IFIT1, IFIT2, and RSAD2 in lung tissues from sepsis-induced animal models." (PMID 38239341, 2023).
celiac disease (4 papers, 2020 to 2024). An autoimmune genetic disorder with an unknown pattern of inheritance that primarily affects the digestive tract. "Of note, the human homologs of four of the CD11b+ DC Runx3 targets, CD300LF, IFIH1, IRF4 and SLC22A5 (mouse Slc22a21) harbored SNPs associated with IBD, CD, UC and/or celiac disease and the two former genes are common Runx3 targets in RM and CD11b+ DC." (PMID 32453801, 2020). "Ten of these cDC2 high-confidence Runx3 targets were common to those in RM and human homologs of four, CD300LF, IFIH1, IRF4 and SLC22A5 (mouse Slc22a21) harbored SNPs associated with IBD, CD, UC and/or celiac disease." (PMID 32453801, 2020).
Hashimoto thyroiditis (4 papers, 2009 to 2024). An autoimmune disorder caused by the production of autoantibodies against thyroid tissue. "Five of the most significant hits after HLA—TNFSF11, CEP43, LPP, C12orf42, and IFIH1—and ten overall coincide with the same direction of effect as seen in the FinnGen and/or UKBB autoimmune hypothyroidism GWAS." (PMID 38776927, 2024).
Hypertension (4 papers, 2013 to 2024). The presence of chronic increased pressure in the systemic arterial system. "Our data indicating that the IFIH1 rs1990760 polymorphism is possibly associated with AH in T1DM patients but not in patients with T2DM may be suggestive that the role of this gene in hypertension is dependent of an immune attack as occurring in the development of T1DM or PE." (PMID 24386202, 2013).
inflammatory bowel disease (4 papers, 2022 to 2025). A spectrum of small and large bowel inflammatory diseases of unknown etiology. "Gain-of-function variants in IFIH1 cause a spectrum of neuroimmunological disorders associated with upregulated Type 1 interferon signaling; loss-of-function variants cause monogenic inflammatory bowel disease." (PMID 40996888, 2025). "IFIH1 variants were significantly enriched in children with Very Early Onset Inflammatory Bowel Disease (VEOIBD) compared to the control." (PMID 35795789, 2022). "The trans-eQTLs contributing to this association with GATE scores for ISGs include IFIH1, IKZF1, and CARD9, previously reported as GWAS hits for inflammatory bowel disease." (PMID 40996888, 2025).
pneumonia (4 papers, 2021 to 2024). An acute, acute and chronic, or chronic inflammation focally or diffusely affecting the lung parenchyma, caused by an infection in one or both of the lungs (by bacteria, viruses, fungi, or mycoplasma.). "Previous studies have highlighted the importance of IFIH1 in regulating macrophage polarisation in ARDS triggered by pneumonia." (PMID 39313944, 2024).
primary immunodeficiency (4 papers, 2021 to 2025). "Experiments have shown that the deficiency of IFIH1 can lead to primary immunodeficiency, which manifests as extreme susceptibility to common respiratory RNA viruses, such as human respiratory syncytial virus and rhinoviruses." (PMID 34920753, 2021).